MOG (myelin oligodendrocyte glycoprotein)
Diseases named in the same sentence as MOG in open-access papers (continued):
Sharing a sentence is not in itself a finding about the gene and the disease.
encephalitis (continued). "Cases of N-methyl-Aspartate receptor (NMDAR) encephalitis as well as MOG antibody-associated encephalitis have been described." (PMID 36865695, 2023). "The patient was diagnosed with anti-MOG antibody-associated unilateral cortical encephalitis with bilateral meningeal involvement." (PMID 36831826, 2023). "FLAIR hyperintense lesions in anti-MOG-associated encephalitis with seizures (FLAMES) is a clinical phenotype of MOG antibody-associated CCE that has been reported since 2017." (PMID 37960781, 2023). "There have also been case reports of COVID‐19‐associated anti‐NMDA‐R10, 11 and anti‐MOG encephalitis." (PMID 36950670, 2023). "This also indicated that more and more patients, diagnosed with the central demyelinating disease before, are now finely diagnosed as MOG antibody-associated disorder or anti-NMDAR encephalitis." (PMID 37407586, 2023). "Anti-NMDAR encephalitis was the most commonly seen among the patients, followed by MOG antibody-associated disorders and autoimmune GFAP astrocytopathy." (PMID 37153594, 2023). "This case illustrates acute onset encephalitis in an adolescent found to have MOG antibody-associated ADEM." (PMID 37465442, 2022). "Encephalitis with Anti-myelin oligodendrocyte glycoprotein (MOG) antibodies: Anti-MOG-associated disease is a recently identified autoimmune disorder that occurs in both adults and children as CNS demyelination." (PMID 35327518, 2022). "Anti-N-methyl-D-aspartate-receptor (NMDAR) encephalitis and Myelin Oligodendrocyte Glycoprotein (MOG) associated disorders are both immune-mediated inflammatory disorders of the central nervous system." (PMID 36384491, 2022). "With the widespread application of MOG antibody detection, reports of encephalitis associated with MOG antibodies are increasing." (PMID 35280998, 2022). "All patients with MOG antibodies had unilateral cortical FLAIR-hyperintense lesions in MOG-associated encephalitis with seizures subtypes of MOG-associated disease." (PMID 36569937, 2022). "Different from classical ADEM, MOG antibody-associated encephalitis is well-circumscribed and cortical-based in neuroimaging, so it is called cortical encephalitis or MOG antibody-associated autoimmune encephalitis (AE) by relevant researchers." (PMID 36688157, 2022). "Firstly, a larger cohort of patients can better represent the general features of MOG-antibody-associated encephalitis." (PMID 34691028, 2021). "“FLAMES” is a new term used to characterise the clinical and radiological syndromes of cortical FLAIR-hyperintense lesions in anti-MOG-Ab-associated encephalitis with seizures." (PMID 35046784, 2021). "Cortical T2-weighted fluid-attenuated inversion recovery (FLAIR)-hyperintense lesions in anti-myelin oligodendrocyte glycoprotein (MOG)-associated encephalitis with seizures (FLAMES) are mostly unilateral and rarely spread to the bilateral cortex and meninges." (PMID 34054711, 2021). "Presently, unilateral cortical T2-FLAIR hyperintensities with epileptic seizure were regarded as a characteristic of anti-MOG-associated encephalitis." (PMID 34011131, 2021). "Coexisting anti-NMDAR and MOG antibody (anti-NMDAR-IgG+/MOG-IgG+)-associated encephalitis have garnered great attention." (PMID 34512521, 2021). "Herein, we report 13 cases with encephalitic symptoms and positive MOG-ab to describe the clinical and imaging features of MOG-ab-associated encephalitis (MOG-E)." (PMID 34691028, 2021). "Previously reported adult cases with anti-MOG antibody associated bilateral medial frontal cortical encephalitis." (PMID 33391163, 2020). "Testing our patients for MOG antibody-associated encephalomyelitis/encephalitis was implemented since 2017." (PMID 33264341, 2020). "Vascular involvement has also been suggested in other forms of anti-MOG antibody-associated encephalitis." (PMID 33391163, 2020).
encephalitis (continued). "Recently, it was reported that transient subcortical hypointensity on T2WI may occur more frequently in encephalitis associated with myelin oligodendrocyte glycoprotein (MOG) antibody-associated disease compared to other causes of encephalitis." (PMID 40551946, 2025). "MOG-encephalitis seems to be the most commonly associated encephalitis with DWM in our review." (PMID 40648981, 2025). "This occurs, for instance, in reports of Myelin oligodendrocyte glycoprotein antibody-associated disease (MOGAD) encephalitis and status epilepticus, where dark white matter (DWM) appears in the imaging but is not mentioned in the figure legends, and is consequently overlooked." (PMID 40648981, 2025). "TCZ could serve as a viable therapeutic alternative for individuals with myelin oligodendrocyte glycoprotein (MOG) antibody-associated encephalitis." (PMID 40301313, 2025). "The most commonly encountered form of encephalitis associated with DWM is anti-MOG encephalitis." (PMID 40648981, 2025). "Encephalitis with normal brain MRI may be regarded as a potential new spectrum associated with MOG antibodies, meriting additional exploration and consideration." (PMID 40078175, 2025). "In children and young adults, ADEM and MOG-associated encephalitis may present with monophasic or multiphasic ADEM with cerebral symptoms of encephalopathy, including decreased levels of consciousness (100%) and seizures (30–60%)." (PMID 40943458, 2025). "This study aims to report the phenomenon of Myelin oligodendrocyte glycoprotein antibody-associated encephalitis induced by Mycoplasma pneumoniae infections and promote the potential benefits of combining early immunotherapy and anti-M—pneumoniae therapy for these patients." (PMID 39334394, 2024). "However, Myelin oligodendrocyte glycoprotein Immunoglobulin G (MOG-IgG) -associated encephalitis due to M. pneumoniae infections was rarely reported previously." (PMID 39334394, 2024). "pneumoniae therapy for patients with MOG-IgG-associated encephalitis." (PMID 39334394, 2024). "FLAIR-hyperintense lesions in anti-myelin oligodendrocyte glycoprotein (MOG)-associated encephalitis with seizures (FLAMES) is a rare clinical phenotype of anti-MOG; immunoglobulin G-associated disease is often misdiagnosed as viral encephalitis in the early stages." (PMID 37960781, 2023). "Therefore, the aim of this study was to present a case of MOG antibody associated encephalitis (MOGAE) following SARS-CoV-2 infection and to review the literature on other MOGADs with similar clinical presentation." (PMID 37638199, 2023). "Interestingly, encephalitis associated with anti-MOG has been observed in both adult and pediatric populations." (PMID 37954587, 2023). "Moreover, anti-NMDAR encephalitis and MOG antibody-associated disorder are new diagnostic diseases proposed in recent years." (PMID 37407586, 2023). "Focal seizures are more common in children with MOG antigen-associated encephalitis, suggesting that seizure types in MOG antibody-associated encephalitis might be age-related." (PMID 36688157, 2022). "In 2019, we systematically reviewed the literature to better characterize this unique syndrome and proposed the term unilateral cortical FLAIR-hyperintense Lesions in Anti-MOG-associated Encephalitis with Seizures (FLAMES), which has since been adopted in the literature." (PMID 36341089, 2022). "Five of the 10 patients had a history of fever with seizures, 4 of whom had eliminated intracranial infection according to the results of cerebrospinal fluid (CSF) examinations, and the other patient was diagnosed with anti-myelin oligodendrocyte glycoprotein (MOG) -associated encephalitis." (PMID 36440324, 2022). "One patient developed an MOG antibody-associated encephalitis." (PMID 36010650, 2022).
encephalitis (continued). "Anti-MOG antibodies have been associated with encephalitis (supplement), similar to our case presentation, leading to potentially life-threatening complications including respiratory impairment, while other cases show a less severe course with good treatment response (supplement)." (PMID 34635185, 2021). "Furthermore, 28% (5/18) of patients with anti-MOG antibody-associated encephalitis had unilateral cerebral cortical lesions, and 33% (6/18) had frontal and/or parietal cortical lesions close to the cerebral falx." (PMID 33391163, 2020). "MOG-IgG-associated encephalomyelitis and isolated encephalitis represent important clinical syndromes associated with MOG-IgG and may be a bridging element in the emerging spectrum of MOG-IgG-associated syndrome." (PMID 29670575, 2018). "Furthermore, seizures and encephalitis-like presentations are more common in MOG antibody-associated disorders compared to AQP-4 antibody positive diseases." (PMID 30555462, 2018). "In addition, seizureis closely related to MOG antibody-associated encephalitis." (PMID 36688157, 2022). "The observation group consisted of patients with anti-NMDAR encephalitis who tested positive for serum MOG-antibodies [MOG-Ab (+)], while the reference group included patients who tested negative for serum MOG-antibodies [MOG-Ab (-)]." (PMID 41676106, 2026). "The highest proportion of MOG-Abs was detected in the cortical encephalitis phenotype, with positivity rates of 71.4% and 85.7% on the Fixed-CBA and Live-CBA, respectively." (PMID 41515652, 2026). "The research results also indicated that male patients with anti-NMDAR encephalitis were more frequently had overlapping anti-MOG antibodies (30.00% vs. 0.00%)." (PMID 41584103, 2025). "As already discussed, important clues exist towards etiologies such as NKH, anti-MOG encephalitis, and SDH." (PMID 40648981, 2025). "CSF analysis supported the diagnoses of MOG antibody-associated encephalitis (PT-7 and PT-23) and GABAAR antibody-associated encephalitis (PT-25)." (PMID 40342619, 2025). "FLAMES, or FLAIR hyperintense lesions, in anti-MOG encephalitis with seizures, are more prominent in patients with focal or generalized seizures." (PMID 40547008, 2025). "MOG antibodies positive encephalitis with normal brain MRI can easily be misdiagnosed as intracranial infection, leading to delayed treatment." (PMID 40078175, 2025). "Specifically, females, patients with serum MOG antibody titers ≥1:32, those with cortical encephalitis phenotype, and those who received inadequate maintenance treatment after the first onset had a higher risk of relapse." (PMID 40098969, 2025). "A total of 4 independent risk factors for predicting relapse were identified: female sex (P=0.040), cortical encephalitis phenotype (P=0.032), serum MOG antibody titer ≥1:32 (P=0.007), and immunosuppressive therapy after the first onset (P= 0.045)." (PMID 40098969, 2025). "In the most extensive case series, 95% of MOG-encephalitis patients presented with DWM adjacent to the cortical lesions." (PMID 40648981, 2025). "Two of these patients were diagnosed with anti‐NMDAR encephalitis, one had anti‐MOG Ab, and the other had anti‐GFAP Ab." (PMID 40583162, 2025). "One patient had no documented relevant clinical symptoms, while the other displayed the typical clinical presentation of anti-LGI1 encephalitis, with a baseline MOG-IgG titer of 1:100." (PMID 40703404, 2025). "Here, we summarized the clinical significance of MOG antibodies positive encephalitis with normal brain MRI for a better understanding of its diagnosis, treatment and prognosis." (PMID 40078175, 2025). "A recent study has identified MOG-encephalitis as the most prevalent subtype of autoimmune encephalitis in children." (PMID 41208985, 2025). "Patients with overlapping MOG antibodies showed cerebral cortical encephalitis, which was easily misdiagnosed as viral encephalitis." (PMID 40028323, 2025).
encephalitis (continued). "We report a case of a 63-year old woman with SWS who developed left-sided hemiparesis and was finally diagnosed with myelin-oligodendrocyte glycoprotein (MOG) antibody-positive encephalitis." (PMID 38292807, 2024). "Steroid therapy can be effective in the acute stage of anti-NMDAR and anti-MOG antibody overlapping encephalitis." (PMID 38895128, 2024). "Recently, cases of overlapping encephalitis caused by anti-N-methyl-D-aspartate receptor (anti-NMDAR) and anti-myelin oligodendrocyte glycoprotein (MOG) antibodies have been reported, and their clinical characteristics are gradually becoming clear." (PMID 38895128, 2024). "We present the case of a 25-year-old man with anti-NMDAR and anti-MOG antibody overlapping encephalitis who showed considerable improvement after steroid treatment." (PMID 38895128, 2024). "Our study suggest that steroid therapy is beneficial for acute phase treatment of anti-NMDAR and anti-MOG antibody overlapping encephalitis." (PMID 38895128, 2024). "Despite negative imaging findings, elevated serum MOG antibody titers and pleocytosis in cerebrospinal fluid (CSF) analysis suggested MOG antibody encephalitis." (PMID 39493140, 2024). "SWS and MOG antibody-positive encephalitis share similar clinical findings of stroke-like symptoms and leptomeningeal enhancement on MRI." (PMID 38292807, 2024). "To gain a deeper understanding of the efficacy of steroids in managing this condition, we conducted a literature review of cases of anti-NMDAR and anti-MOG antibody double-positive encephalitis that were treated with steroids during the acute phase." (PMID 38895128, 2024). "Clinically, patients who are double positive for both anti-NMDAR and MOG antibodies exhibit symptoms of both anti-NMDAR encephalitis and MOGA, with convulsions, mental and behavioral abnormalities being as the common symptoms in the acute stage." (PMID 37960781, 2023). "Previous studies reported 15 (16.85%) pediatric patients with anti-NMDAR encephalitis positive for MOG antibodies and 5 (11.9%) MOG-AD patients positive for anti-NMDAR antibodies." (PMID 38249740, 2023). "A previous study found simultaneous or sequential demyelinating events in 23 (3.3%) of 691 anti-NMDAR encephalitis patients, and 9 (1.3%) of these patients tested positive for MOG antibodies." (PMID 38249740, 2023). "In summary, the coexistence of anti-NMDAR and MOG antibodies can lead to the overlap of clinical phenotypes of anti-NMDAR encephalitis and MOG-AD." (PMID 38249740, 2023). "This indicated that the phenotypes of anti-NMDAR encephalitis were atypical and easily complicated with CNS demyelinating manifestations after the coexistence of MOG and anti-NMDAR antibodies." (PMID 38249740, 2023). "Anti-NMDAR encephalitis was the most common subtype (97 cases), followed by MOG-AD (48 cases) and autoimmune GFAP-A (30 cases)." (PMID 37153594, 2023). "The proportion of abnormal cerebrospinal fluid protein cases in the MOG-AD group was significantly higher than that in the anti-NMDAR encephalitis group (p < 0.05)." (PMID 38249740, 2023). "To date, anti-NMDAR encephalitis has been identified as the most common subtype in pediatric patients, but reports of anti-MOG antibody disease are increasingly frequent." (PMID 36747031, 2023). "Relatively, the distributions of individual features are more concentrated in MOG antibody-associated disease and anti-NMDAR encephalitis." (PMID 37407586, 2023). "Other long-term AEs included viral encephalitis at month 18 and MOG + encephalomyelitis at month 30 of patient 1, and both were treatable." (PMID 36681817, 2023). "The median time between onset of encephalitis and MOG-positivity was 0 months, ranging from -240 (indicating positive MOG IgG before onset of encephalitis) to 35 months." (PMID 36384491, 2022). "Here, we report the case of male patient with anti-NMDAR encephalitis who developed MOG and Caspr2 IgG during the disease course." (PMID 36384491, 2022).
encephalitis (continued). "Phase 2 clinical trials are ongoing in patients with anti-LGI1 encephalitis (NCT04875975) and myelin oligodendrocyte glycoprotein (MOG) antibody-associated disease (NCT05063162)." (PMID 35060089, 2022). "A broad spectrum of associated clinical phenotypes that can be addressed with anti-MOG antibodies has been shown, and some cases of encephalitis with seizures have been reported." (PMID 36188368, 2022). "Encephalitis was the predominant phenotype when MOG-IgG coexisted with NMDAR-IgG, probably accompanied by imaging features of demyelination." (PMID 36009058, 2022). "Data of clinical and radiological presentations of MOG-positive anti-NMDAR-encephalitis are still scarce and were published in form of case series and reports." (PMID 36384491, 2022). "Pooled data from a recent meta-analysis demonstrated that approximately 9% of MOG-IgG-positive patients had coexisting NMDAR-IgG, and 7% of patients with anti-NMDAR encephalitis were positive for MOG-IgG." (PMID 36009058, 2022). "As the name suggests, unilateral involvement is typically observed, although development of bilateral cortical encephalitis with anti-MOG positivity has been described in a small number of patients (discussed later)." (PMID 36341089, 2022). "To date, there are only 10 COVID patients with definite encephalitis associated with known neuronal antibodies 8 NMDAR-Ab, one CASPR2-Ab, and one MOG-Ab." (PMID 35353232, 2022). "In an analysis of 691 cases of anti-NMDAR encephalitis, 12 cases were found to be MOG-Ab-positive at the same time." (PMID 35046784, 2021). "The patients with co-existing MOG-Ab tended to have milder conditions than ones with typical anti-NMDAR encephalitis, in agreement with previous studies." (PMID 34268281, 2021). "Unilateral cortical FLAIR-hyperintense lesions in anti-MOG-associated encephalitis with seizures (FLAMES) is a less common, but quite characteristic clinical-MRI phenotype seen with MOG autoantibodies." (PMID 34305787, 2021). "Case Report: We present a case of anti-NMDAR encephalitis combining with anti-MOG CNS demyelination following recurrent CNS demyelination." (PMID 33716942, 2021). "Repeat autoantibodies test indicated cerebrospinal fluid (CSF) NMDAR antibodies coexisted with MOG-Abs simultaneously, suggesting the diagnosis of anti-NMDAR encephalitis with anti-MOG CNS demyelination." (PMID 33716942, 2021). "It is worth noting that anti-MOG antibodies can also be detected in other autoantibody-associated encephalitis, such as anti-NMDAR encephalitis." (PMID 34011131, 2021). "We describe a unique case of a young man with Covid-19 and transient MOG-positive encephalitis, with a benign course." (PMID 34706651, 2021). "In a single-centre cohort study from China, 20.7% of MOG-Ab-positive patients had typical encephalitis symptoms, and 72.2% had cortical changes during the course of encephalitis." (PMID 35046784, 2021). "Myelin oligodendrocyte glycoprotein-antibody (MOG-ab)-associated disease (MOGAD) has highly heterogenous clinical and imaging presentations, in which encephalitis is an important phenotype." (PMID 34691028, 2021). "Here, we describe a unique case of a young man with Covid-19 and transient MOG-positive encephalitis, with a benign course." (PMID 34706651, 2021). "The role of spectrum of myelin oligodendrocyte glycoprotein (MOG) antibody encephalitis, which has begun to stand out as a separate entity in recent years, is attracting increasing attention from researchers." (PMID 33264341, 2020). "Group 3 included 50 randomly selected patients with typical anti-NMDAR encephalitis (three MOG antibody-positive cases)." (PMID 31507515, 2019). "Group 1 included 12 patients whose anti-NMDAR encephalitis was preceded or followed by independent neuromyelitis or demyelinating syndromes (seven cases, all anti-MOG antibody-positive)." (PMID 31507515, 2019). "Co-positive MOG antibody was relatively common in anti-NMDAR encephalitis, which was related to high relapse rate." (PMID 31507515, 2019).